SLC7A11 (solute carrier family 7 member 11)
Diseases named in the same sentence as SLC7A11 in open-access papers (continued):
Sharing a sentence is not in itself a finding about the gene and the disease.
gastric cancer (94 papers, 2015 to 2026). A primary or metastatic malignant neoplasm involving the stomach. "Similarly, SLC7A11—a critical regulator of the cystine/glutamate antiporter system—has been implicated in ferroptosis regulation through the PI3K/AKT pathway in gastric cancer, where its knockdown enhances ferroptosis sensitivity by increasing lipid peroxidation." (PMID 40732297, 2025). "HIF-1α regulates the expression level of SLC7A11 through lncRNA, which reduces the amount of ROS and iron accumulation in gastric cancer cells, and makes them less sensitive to ferroptosis." (PMID 40959280, 2025). "As a result of our analysis, we delved into the expression of SLC7A11 in various gastric cancer cell lines, and we found that SLC7A11 protein levels surged across the board in these lines, with the sole exception being the HGC cells." (PMID 40539058, 2025). "POU6F1 and lncRNA-CASC2, through FMRP, regulate the SOCS2/SLC7A11 signaling axis to modulate ferroptosis in gastric cancer, suggesting a novel mechanism for controlling cancer stem-like cell survival and potentially targeting cancer stemness in this disease." (PMID 40271197, 2025). "The previous study has unveiled that the co-administration of ursolic acid and sorafenib exhibits a synergistic impact by upregulating ROS levels and downregulating the expression of SLC7A11 in gastric cancer and colon cancer cells." (PMID 40535804, 2025). "Vice versa, ERBB3 inhibition with TX1-85-1 induced lipid peroxidation in gastric cancer cells, with effects most pronounced in cell lines expressing higher SLC7A11 levels." (PMID 40846695, 2025). "CD44v interacts with SLC7A11 and stabilizes its expression on the plasma membrane, inducing resistance to 5-fluorouracil in gastric cancer." (PMID 38739940, 2024). "Ursolic acid and oleanolic acid in ACP, as well as JDA from Jiyuan Rabdosia rubescens, promote ferroptosis in gastric cancer cells by suppressing SLC7A11 and GPX4 expression." (PMID 38292937, 2024). "It affects ferroptosis and controls the expression of SLC7A11, a target of miR-375 in gastric cancer." (PMID 38887390, 2024). "SLC7A11 transcripts were detected in seven gastric cancer cell lines and one immortalised stomach epithelial cell line." (PMID 39437660, 2024). "A similar effect was observed in gastric cancer cells treated with the STAT3 inhibitor W1131 caused by reduced STAT3 occupancy on the GPX4, SLC7A11, and FTH1 promoters." (PMID 38539832, 2024). "For instance, CircRAB11FIP1 promotes ovarian cancer via miR‐129/DSC1 axis (Zhang, Zhu, & Hu, 2021), circEPSTI1 upregulates SLC7A11 expression in cervical cancer by miR‐375 and circ_0110389 accelerates gastric cancer through miR‐127‐5p/SORT1." (PMID 39632246, 2024). "MiR-375 inhibited the stemness characteristics of gastric cancer cells by targeting SLC7A11-mediated ferroptosis." (PMID 38811540, 2024). "The inhibition of SLC7A11 reduced chemoresistance and stemness in colon cancer and gastric cancer cells by triggering ferroptosis." (PMID 37433225, 2023). "Hypoxia-induced HIF-1α/lncRNA-PMAN prevents ferroptosis in gastric cancer by enhancing SLC7A11 mRNA stability and increasing the expression of SLC7A11 at the posttranscriptional level." (PMID 37213276, 2023). "Next, we further evaluated the impact of levobupivacaine/miR-489-3p/SLC7A11 axis on gastric cancer progression in vitro." (PMID 34177591, 2021). "levobupivacaine-upregulated miR-489-3p enhanced ferroptosis of gastric cancer cells by targeting SLC7A11." (PMID 34177591, 2021).
gastric cancer (continued). "Overall, this work disclosed a potential therapeutic function of local anesthetic levobupivacaine in gastric cancer, and provided the possible mechanisms of miR-489-3p/SLC7A11 involved in this process." (PMID 34177591, 2021). "Our data showed that miR-489-3p upregulated by levobupivacaine contributed to ferroptosis of gastric cancer cells by targeting SLC7A11." (PMID 34177591, 2021). "Accordingly, we concluded that the local anesthetic levobupivacaine induced ferroptosis of gastric cancer cells to repress gastric cancer cell growth by miR-489-3p/SLC7A11 axis." (PMID 34177591, 2021). "It indicates an innovative mechanism of levobupivacaine/miR-489-3p/SLC7A11 axis in the regulation of gastric cancer." (PMID 34177591, 2021). "In gastric cancer cells, circHIPK3 contributes to cisplatin resistance by inhibiting autophagy-dependent ferroptosis, while silencing circHIPK3 enhances ferroptosis through the miR-508-3p/Bcl-2/Beclin1/SLC7A11 axis, reducing cisplatin resistance." (PMID 40630134, 2025). "Interestingly, miR-375-3p can also induce ferroptosis by targeting solute carrier family 7 member 11 (SLC7A11), a negative regulatory factor of ferroptosis, and thus attenuate the stemness of gastric cancer cells and cervical cancer progression 20-22." (PMID 39897035, 2025). "Furthermore, in the case of bladder cancer and gastric cancer, high SLC7A11 expression correlates with poorer survival in cisplatin‐treated patients." (PMID 40784667, 2025). "Comparing the expression of key proteins involved in ferroptosis in different cells, GPX4 and downstream SLC7A11 may be valuable evaluation indicators for gastric cancer cells (Hgc27 and MKN45)." (PMID 39991579, 2025). "We identified numerous gastric cancer cell lines and observed a substantial increase in slc7a11." (PMID 40539058, 2025). "Interestingly, circHIPK3/miR508-3p interaction can modulate SLC7A11 activity and induce cisplatin resistance in gastric cancer." (PMID 40061896, 2025). "Salubrinal induces resistance to cisplatin in gastric cancer cells by upregulating SLC7A11." (PMID 38739940, 2024). "In addition, we plan to design anti-SLC7A9 and anti-SLC7A11 antibody-drug conjugates in a follow-up study, to improve drug targeting of gastric cancer." (PMID 39437660, 2024). "Forty-two gastric cancer samples and paracancerous samples were included, and all cases were detected with glutathione peroxidase 4, nuclear factor erythroid 2-related factor 2, and solute carrier family 7 member 11 by immunohistochemistry." (PMID 37768308, 2023). "In gastric cancer as well, miR-375 was seen targeting SLC7A11, thus inducing ferroptosis." (PMID 37240889, 2023). "Our results showed that knockdown of TRF2 in gastric cancer cells resulted in the downregulation of SLC7A11 and GPX4 expressions at the mRNA and protein levels, while the expression of SLC7A11 and GPX4 recovered after pretreatment with the ferroptosis inhibitor ferrostatin-1." (PMID 37113742, 2023). "Additionally, in SGC7901 gastric cancer cells, levobupivacaine treatment elevated the level of miR-489-3p and further acted as a sponge for SLC7A11 to inhibit its expression, thereby promoting ferroptosis in gastric cancer cells." (PMID 36313359, 2022).
gastric cancer (continued). "For example, lncRNA-PMAN was upregulated by HIF-1α and enhanced the stability of SLC7A11 mRNA, which suppressed the accumulation of reactive oxygen species (ROS) and irons in gastric cancer cells, and thus protected gastric cancer cells from ferroptosis induced by Erastin and RSL3." (PMID 36612069, 2022). "In addition, levobupivacaine, another local anesthetic, was found to inhibit the growth of gastric cancer cells by inducing ferroptosis of gastric cancer cells through miR-489-3p/SLC7A11 axis." (PMID 36408273, 2022). "Therefore, we concluded that the local anesthetic levobupivacaine induced ferroptosis of gastric cancer cells to repress gastric cancer cell growth by miR-489-3p/SLC7A11 axis." (PMID 34177591, 2021). "Levobupivacaine/miR-489-3p/SLC7A11 axis attenuates gastric cancer cell proliferation in vitro." (PMID 34177591, 2021). "We then detected whether SLC7A11 was involved in miR-489-3p-enhanced ferroptosis of gastric cancer cells." (PMID 34177591, 2021). "Taken together, dysregulated RELB, IL-32, and SLC7A11 may mediate inflammatory responses, oxidative stress levels or cellular energy metabolism to potentiate the ability of H. pylori to induce gastric carcinoma." (PMID 32457731, 2020). "For example, miR-375, a tumor suppressor in various tumors, suppresses gastric cancer (GC) stemness by inducing SLC7A11-dependent ferroptosis." (PMID 41601687, 2026). "Therefore, we speculate that GPX4 and downstream SLC7A11 are important ferroptosis intervention proteins in gastric cancer cells (Hgc27 and MKN45)." (PMID 39991579, 2025). "Similarly, tanshinone IIA suppressed gastric cancer cell stemness via SLC7A11-mediated ferroptosis." (PMID 37964867, 2023). "The clinical anesthetic propofol exerts dual regulation on GPX4 and SLC7A11 expression via the miR‐125b‐5p/STAT3 axis, exhibiting proferroptotic effects in gastric cancer models while demonstrating Fe homeostasis protection in neuroblastoma." (PMID 40919133, 2025). "Previous studies have established that Stat3 interacts with the promoters of GPX4, SLC7A11, and FTH1, thereby modulating their expression levels in gastric cancer, which leads to the formation of a Stat3-ferroptosis regulatory axis." (PMID 41341590, 2025). "These insights establish SLC7A11 as a critical node connecting ferroptosis regulation and PI3K/AKT pathway activity, suggesting its potential as a therapeutic target in gastric cancer." (PMID 40740483, 2025). "SLC7A11 knockdown reduced cystine transport into cells and hindered intracellular cystine and GSH metabolism, and increased lipid ROS levels in gastric cancer cells, which is consistent with our study." (PMID 40724917, 2025). "The induction of ferroptosis occurs by the K48 ubiquitination and subsequent degradation of the solute carrier family 7 member 11 (SLC7A11), and is a particularly intriguing aspect of TRIM7’s role in gastric cancer cells." (PMID 39205259, 2024). "Meanwhile, we conducted western blotting to investigate the correlation between ABCC2 expression and SLC7A11 and GPX4 in gastric cancer cell lines under different nutritional conditions." (PMID 39095325, 2024). "These metabolites enhance ROS accumulation by suppressing the expression of SLC7A11 and GPX4 in gastric cancer cells, ultimately inducing ferroptosis." (PMID 38292937, 2024). "Therefore, we speculated that SLC7A9 played a more important role in gastric cancer than SLC7A11." (PMID 39437660, 2024). "For example, in gastric cancer cells, HIF-1α has been shown to inhibit ferroptosis by increasing the expression of SLC7A11 at the post-transcriptional level and stabilizing SLC7A11 mRNA at the transcriptional level." (PMID 37598126, 2023). "An analogue mechanism was observed in gastric cancer cells for levobupivacaine, which exerts its anticancer effect by upregulating miR-489-3p that, in turn, binds to the 3′-UTR of SLC7A11 and reduces its levels." (PMID 37240889, 2023).
gastric cancer (continued). "This retrograde signaling contributed to mitochondrial dysfunction-induced cisplatin resistance in a gastric cancer model through activation of the eIF2α-ATF4 pathway and consequent induction of SLC7A11 expression." (PMID 33401748, 2021). "Pharmacological inhibition of SLC7A11 with sulfasalazine (SSZ) or erastin, genetic silencing of SLC7A11 expression, or inhibition of GSH synthesis with buthionine sulphoximine (BSO) restores cisplatin sensitivity in gastric cancer cells." (PMID 33401748, 2021). "The xc− system consisting of CD98hc and xCT (SLC7A11) influxes cystine and effluxes glutamate, which in turn regulates intracellular GSH and ROS levels in gastric cancer cells." (PMID 31501417, 2019). "In gastric cancer patients, STAT3 can bind to the consensus DNA response elements within the promoters of NR-related genes (GPX4, SLC7A11, and FTH1) and promote the expression of these ferroptosis-negative regulators, thereby establishing a negative STAT3–ferroptosis regulatory axis (Bottom left)." (PMID 41513612, 2026). "For example, inhibition of STAT3 could regulate GPX4, SLC7A11 and FTHI to induce ferroptosis, which can restore the sensitivity of gastric cancer cells to chemotherapy drugs." (PMID 38347435, 2024). "In our previous study, DRN analysis showed that SLC7A9, but not SLC7A11, was a key regulator in gastric cancer." (PMID 39437660, 2024). "Additionally, propofol was found to decrease GPX4 and SLC7A11 protein levels by suppressing STAT3 expression, decelerating gastric cancer growth in vivo." (PMID 38111578, 2023). "In another attempt to investigate the role of ferroptosis-related in other cancers, we performed the survival analysis of SLC7A11, MSC-AS1 and MYLK-AS1 in gastrointestinal cancer including colon cancer, esophageal cancer, liver cancer, pancreatic cancer and stomach cancer." (PMID 34568075, 2021). "SLC7A11 combined with CD44 (cancer cell stem marker) controls the reduced glutathione and defense against reactive oxygen species in a transgenic mouse model of gastric cancer." (PMID 33362856, 2020). "In gastric cancer, STAT3 regulates ferroptosis primarily through its own histone acetylation, which increases its gene-level expression and promotes the expression of downstream direct targets GPX4, SLC7A11, and FTH1, thereby exerting an anti-ferroptotic effect." (PMID 41513612, 2026). "STAT3 knockdown in gastric cancer cells provoked a significant inhibition of GPX4, SLC7A11, and FTH1 at both the mRNA and protein levels, and also increased lipid peroxidation and ROS, and enhanced intracellular Fe2+, thus reducing the GSH/GSSG ratio in gastric cancer cells." (PMID 38539832, 2024).
gastric cancer (continued). "The WB results of ferroptosis key protein showed that compared with GES1 and MC, there were no significant changes in FSP1 and DHODH in gastric cancer cells (Hgc27 and MKN45), slight changes in GPX4, no significant changes in SLC7A11." (PMID 39991579, 2025). "WB results showed that compared with the blank group added with RSL3, the M2c co culture group added with RSL3 gastric cancer cells (Hgc27 and MKN45) showed no significant decrease in GPX4 protein and downstream SLC7A11 protein." (PMID 39991579, 2025). "In gastric cancer, STAT3 directly bound to the promoters of negative ferroptosis regulators (GPX4, SLC7A11, and FTH1) and modulated their expression." (PMID 38341410, 2024). "Gastric cancer tissues showed more positive staining with GPX4, NRF2, and SLC7A11 when compared with adjacent non-tumor tissues; GPX4 and NRF2 staining was mainly seen in the nucleoplasm or cytoplasm, while SLC7A11 staining patterns were mainly cytoplasmic." (PMID 37768308, 2023).